SPAG8 (sperm associated antigen 8)
Description:
Microtubule inner protein (MIP) part of the dynein-decorated doublet microtubules (DMTs) in cilia axoneme, which is required for motile cilia beating. Plays a role in spermatogenesis by enhancing the binding of CREM isoform tau to its coactivator FHL5 and increasing the FHL5-regulated transcriptional activation of CREM isoform tau (By similarity). Involved in the acrosome reaction and in binding of sperm to the zona pellucida (By similarity). Plays a role in regulation of the cell cycle by controlling progression through the G2/M phase, possibly by delaying the activation of CDK1 which is required for entry into mitosis. May play a role in fertility and microtubule formation through interaction with RANBP9.
Synonyms: hSMP-1; HSD-1; BS-84; SPAG3; CT142; CILD28; SMP1
Tractability: Small molecule: a structure with a bound ligand is known.
Gene: Protein-coding gene on chromosome 9 (35,808,045 to 35,812,272, reverse strand). Ensembl gene ENSG00000137098.
Subcellular location: Cytoplasm; Nucleus; Cytoplasmic vesicle, secretory vesicle, acrosome; Cytoplasm, cytoskeleton, microtubule organizing center; Cytoplasm, cytoskeleton, spindle; Cytoplasm, cytoskeleton, cilium axoneme; Cytoplasm, cytoskeleton, flagellum axoneme
Subcellular location (Human Protein Atlas): Acrosome; End piece; Equatorial segment; Primary cilium; Cytosol; Nucleoplasm; Principal piece
Gene Ontology:
Molecular function: protein binding; microtubule binding
Biological process: flagellated sperm motility; positive regulation of transcription by RNA polymerase II
Cellular component: axonemal microtubule; cilium; axonemal A tubule inner sheath; cytoplasm; membrane; nucleus; sperm flagellum; acrosomal vesicle; axoneme; microtubule organizing center; spindle
Genetic constraint (gnomAD): Loss-of-function variants: 38 observed, 47.78 expected, observed/expected ratio (o/e) 0.8, 90% interval 0.61 to 1.04. The upper end of that interval is the gene's LOEUF score, 1.04, which puts it in group 4 of 6, group 1 being the genes least tolerant of losing a copy. Missense variants: 569 observed, 636.36 expected, observed/expected ratio (o/e) 0.89, 90% interval 0.83 to 0.96. Synonymous variants: 224 observed, 245.03 expected, observed/expected ratio (o/e) 0.91, 90% interval 0.82 to 1.02.
Homologues: Orthologues: macaque SPAG8 (92% identical), chimpanzee SPAG8 (88% identical), rabbit SPAG8 (68% identical), dog SPAG8 (64% identical), pig SPAG8 (64% identical), mouse Spag8 (58% identical), rat Spag8 (53% identical), zebrafish spag8 (12% identical).
Diseases named in the same sentence as SPAG8 in open-access papers:
SPAG8 is named in the same sentence as 8 diseases in open-access papers, as found by Europe PMC text mining. Sharing a sentence is not in itself a finding about the gene and the disease. The quoted sentences say what the papers report.
infertile (2 papers, 2017 to 2020). "SPAG8 was previously designated as hSMP-1 or HSD-1 and originally isolated from a human testis expression library using antisperm antibodies obtained from the serum of an infertile woman." (PMID 33333720, 2020).
melanoma (2 papers, 2017 to 2018). A malignant, usually aggressive tumor composed of atypical, neoplastic melanocytes. "CTAG1B, BRCA2, and SPAG8 have been previously shown to induce humoral immune response in BC and other cancer patients, ANKRD30BL and COPS4 were previously found to elicit autoantibody response in gastric and thyroid cancer and melanoma." (PMID 30515157, 2018).
SPAG8 also shares sentences with these, for which no sentence is quoted: infection (3 papers); tumor (2); cancer (1); multiple sclerosis (1); proctitis (1); thyroid cancer (1).